CPT1A (carnitine palmitoyltransferase 1A)
Diseases named in the same sentence as CPT1A in open-access papers (continued):
Sharing a sentence is not in itself a finding about the gene and the disease.
gastric cancer (35 papers, 2019 to 2026). A primary or metastatic malignant neoplasm involving the stomach. "Its association with adverse clinical outcomes positions CPT1A as a promising biomarker and potential therapeutic target in gastric cancer management." (PMID 41154605, 2025). "Gene function enrichment analysis of the GEO gastric cancer public database GSE57303 showed that CPT1A is associated with fatty acid metabolism and FAO." (PMID 37416765, 2023). "In gastric cancer, CPT1A is associated with the malignant phenotype of gastric cancer cells, and its higher protein levels tend to predict and shorten the survival time, so it can be used as a good prognostic bioindicator for the diagnosis and treatment of gastric cancer patients." (PMID 39596847, 2024). "Interestingly, gene function enrichment analysis of the GEO gastric cancer public database GSE57303 showed that CPT1A is associated with fatty acid metabolism and FAO." (PMID 37416765, 2023). "Pharmacological inhibition of the PCK/CPT1A significantly suppressed tumor growth in 18F-FDG-PET/CT-negative gastric cancers, as demonstrated in both cell-derived xenograft (CDX) and patient-derived xenograft (PDX) models." (PMID 41888524, 2026). "In gastric cancer, CPT1A succinylates LDHA at K222, thereby inhibiting its degradation and promoting the proliferation and invasion of gastric cancer cells." (PMID 39781339, 2025). "A key enzyme of fatty acid oxidation (FAO), carnitine palmitoyl transferase 1A (CPT1A), is upregulated by an exosomal lncAKR1C2-encoded microprotein, pep-AKR1C2, inducing a metabolic switch towards FAO in gastric cancer." (PMID 39123386, 2024). "Carnitine palmitoyltransferase 1 A (CPT1A) succinylates lactate dehydrogenase A, thus promoting the invasion and proliferation of gastric cancer." (PMID 38835015, 2024). "Of note, CPT1A-mediated activation of fatty acid oxidation increases the proliferation and migration of gastric cancer cells." (PMID 39834822, 2024). "This study provides a scientific basis for TGF-β/SDPR/CPT1A axis as a clinical therapeutic target for patients with gastric cancer." (PMID 37416765, 2023). "The expression levels of SDPR and CPT1A were evaluated using immunohistochemistry analysis of 170 paraffin-embedded gastric cancer specimens and normal tissues." (PMID 37416765, 2023). "Although previous gene microarray analysis and experimental results suggested that CPT1A is a downstream target gene of SDPR, the potential clinical value of CPT1A in gastric cancer was still unclear." (PMID 37416765, 2023). "The results of in vivo experiments further confirmed that CPT1A significantly promoted the metastasis of gastric cancer." (PMID 37416765, 2023). "SDPR was expressed at low levels in gastric cancer, and its expression level decreased relative to the progression of the tumour stage, whereas CPT1A showed the opposite result." (PMID 37416765, 2023). "The purpose of this study was to identify the key role of TGF-β/SDPR/CPT1A signaling axis in gastric cancer metastasis, thus providing a new direction for the exploration of clinical therapeutic targets." (PMID 37416765, 2023). "Transwell experiments and wound-healing experiments confirmed that the downregulation or inhibition of CPT1A significantly inhibited the metastasis of gastric cancer." (PMID 37416765, 2023). "Previous studies reported that S100A10 accumulation was involved in gastric cancer cell invasion and migration through the succinyltransferase CPT1A and SIRT5-mediated desuccinylation." (PMID 34178044, 2021). "In addition, multivariate survival analysis showed that SDPR and CPT1A expression, T grade, and age were independent predictors of prognosis in gastric cancer patients." (PMID 37416765, 2023). "Moreover, carnitine palmitoyltransferase 1A (CPT1A) is found to have lysine succinyltransferase activity upon the succinylation of S100A10 in gastric cancer." (PMID 34050894, 2022).
gastric cancer (continued). "In addition, another study demonstrated that S100A10, a member of the calcium-binding cytoplasmic protein family, can bind to CPT1A at K47 and then be succinylated by it; contributing to the proliferation of gastric cancer cells." (PMID 36359005, 2022). "In addition, CPT1A succinylates lactate dehydrogenase A (LDHA) at K222 that leads to reduced LDHA degradation in gastric cancer and consequently promotes cell invasion." (PMID 36605449, 2022). "Furthermore, CPT1A causes the succinylation of S100A10 at K47, which inhibits ubiquitination and subsequent proteasomal degradation of S100A10, thereby promoting the invasion and migration of gastric cancer." (PMID 39781339, 2025). "In gastric cancer (GC), CPT1A-mediated LDHA-K222succ reduces its binding to SQSTM1 and inhibits the degradation of LDHA, as well as promotes GC invasion and proliferation." (PMID 38882606, 2024). "We found that CPT1A was highly expressed in most tumours according to TCGA microarray analysis, suggesting that CPT1A may play a role in promoting tumours in gastric cancer." (PMID 37416765, 2023). "Therefore, interference with CPT1A, a key regulator of lipid metabolism, may inhibit gastric cancer transformation." (PMID 37416765, 2023). "Protein succinylation mediated by CPT1A has been demonstrated to promote the proliferation and invasion of gastric cancer (GC) by regulating LDHA succinylation." (PMID 36577755, 2022). "CPT1A can promote the proliferation of breast cancer cells by succinylation of enolase 1 and enhance metastasis of gastric cancer (GC) cells by succinylation of S100A10." (PMID 33681201, 2021). "Our previous results showed that succinylation was more a consistent protein modification than crotonylation and acetylation in GC and adjacent tissues, and succinylation of S100A10 by CPT1A promoted human gastric cancer (GC) invasion." (PMID 32859246, 2020). "PCK and CPT1A, the key enzymes which are responsible for remodeling the metabolism, were highly expressed in FDG-PET/CT-negative gastric cancers." (PMID 41888524, 2026). "Specifically, CPT1A promotes the succinylation of S100A10, enhancing the invasive ability of human gastric cancer." (PMID 40070041, 2025). "Furthermore, LDHA was found to be hypersuccinylated at K222 catalyzed by CPT1A in gastric cancer (GC) to promote GC cell proliferation, invasion, and migration." (PMID 38315203, 2024). "In summary, overexpression of SDPR inhibits TGF-β-induced gastric cancer metastasis by inhibiting the key enzyme CPT1A of FAO, which plays an important role in regulating gastric cancer metastasis." (PMID 37416765, 2023). "SDPR regulates the ERK/PPARα signalling axis by interacting with the ERK protein and regulates CPT1A at the transcriptional level, which is involved in FAO in gastric cancer." (PMID 37416765, 2023). "Kaplan-Meier survival analysis showed that gastric cancer patients with high SDPR expression had better disease-free survival (DFS) and OS, while those with high CPT1A expression had the opposite result." (PMID 37416765, 2023). "CPT1 has been extensively studied in a variety of cancers, and overexpression of CPT1A accelerates tumor development by stimulating FAO in prostatic cancer, breast cancer, gastric cancer, and hepatocellular cancer." (PMID 37927468, 2023). "The overexpression of carnitine palmitoyltransferase 1A (CPT1A), an essential enzyme for FAO, increases vimentin and SNAIL and decreases E-cadherin expression in gastric cancer." (PMID 38002286, 2023). "CPT1A succinylated S100A10 at lysine 47, and the degree of succinylation was elevated in human gastric cancer." (PMID 37033619, 2023). "The succinic acidification mimic mutant S100A10(K47E) has also been used to further verify that CPT1A-mediated S100A10 succinylation increases the invasion and migration of gastric cancer cells." (PMID 36359005, 2022).
gastric cancer (continued). "CPT1A and ACSL3, which are responsible for fatty acid oxidation, have been proved to stimulate gastric cancer and hepatocellular carcinoma cell growth and migration." (PMID 33971821, 2021). "S100A10 accumulation, which is regulated by the succinyltransferase CPT1A and SIRT5-mediated desuccinylation, promotes gastric cancer cell invasion and migration." (PMID 31739800, 2019). "Carnitine palmitoyltransferase 1A (CPT1A), by influencing LDHA at K222, increases its succinylation level, inhibiting LDHA degradation, thus enhancing glycolysis and promoting the invasion and proliferation of gastric cancer." (PMID 39781339, 2025). "By analyzing the co-expression correlation between CPT1A, IL-8, CXCL5, STC1 and CD44 in stomach cancer tissues through TCGA database, we found that these genes except CXCL5 were positively correlated with CD44 and were positively associated with at least one MSC markers (ENG, THY1, NT5E)." (PMID 37158903, 2023). "Additionally, CPT1A (carnitine palmitoyltransferase 1A) has a lysine succinyltransferase activity to promote S100A10 succinylation, supporting gastric cancer progression." (PMID 35631199, 2022). "It is still unknown whether the low level of CPT1A also happens in PMs‐CRC with additional sites of metastasis, and other tumors with PM, such as ovarian, pancreatic, and gastric cancer." (PMID 33528867, 2021).
Insulin resistance (35 papers, 2012 to 2025). Increased resistance towards insulin, that is, diminished effectiveness of insulin in reducing blood glucose levels. "And multi-tissue epigenetic analysis has revealed distinct associations between the CPT1A locus and insulin resistance." (PMID 39827095, 2025). "Alterations in both substrates (free fatty acids; FFAs) and products (long chain acylcarnitines) of CPT1a have been associated with insulin resistance." (PMID 37797918, 2023). "In an animal study, mitochondrial dysfunction caused by a high-fat diet was linked to insulin resistance in muscle, implying that excessive CPT1A activity overloads the mitochondria resulting from incomplete oxidation of long-chain fatty acids." (PMID 36501195, 2022). "Moreover, CPT1A P479L T-allele carriers (L479) showed reduced insulin resistance and smaller body size." (PMID 27341449, 2016). "Interestingly, overexpression of an active Cpt-1a was able to ameliorate insulin resistance in mice which could also be associated with the phenotype that was observed in AdipoRonPEG5-treated mice." (PMID 34214600, 2021). "In addition to the FA associations, CPT1A rs80356779 was associated with lower HbA1c, indicating improved glycemic regulation, and with several measures of smaller body size and reduced insulin resistance." (PMID 27341449, 2016). "This benefit was associated with increased hepatic expression of carnitine palmitoyltransferase 1a (Cpt1a), proposed to combat hyperglycemia, insulin resistance, and metabolic syndrome." (PMID 39520540, 2025). "HMGCR and CPT1A, the target gene of miR-93-3p and miR-188-5p, respectively, are closely related not only to insulin resistance but also to abnormal lipid metabolism." (PMID 32802120, 2020). "Previously we reported that the Cpt1a+/− mice were resistant against HFD-induced insulin resistance, but showed hepatosteatosis with increased hepatic CPT1b expression." (PMID 25309812, 2014). "Studies have shown that inhibition of Cpt1a increases lipid deposition and exacerbates insulin resistance when animals are placed on a high-fat diet, whereas overexpression of Cpt1a protects myotubes against lipid-induced insulin resistance." (PMID 23360495, 2013). "Oleate increases insulin signaling and reduces NPY expression and linolenic acid may reduce insulin resistance through the increase in fatty acid oxidation in agreement with our data showing augmented Cpt1a expression in ND IRS2−/− mice." (PMID 34440853, 2021). "In a model of insulin resistance of rats fed a high-fat diet, the administration of the major metabolite of oleuropein, hydroxytyrosol, increases the hepatic mRNA levels of Ppara and its target genes, i.e., fibroblast growth factor 21 and carnitine palmitoyltransferase 1a." (PMID 34445672, 2021). "The DEGs Slc27a1, Cpt1a, Srebf1, and Foxo1 were enriched in insulin resistance pathway and also appeared in the network of top 10 upregulated and downregulated mRNAs, indicating these four mRNAs might play key roles in the development of hyperglycemia and T2D in GK rats at the age of 3 and 4 weeks." (PMID 32095365, 2020). "Among these DMRs, SREBF1, HOXA5, CPT1A, LPIN1, and PHGDH have established roles in adipose tissue biology and insulin resistance." (PMID 33243154, 2020). "In addition, by upregulating the transcription of Cpt1a, Pparα, Mcad, Acsl, and Ppargc1a, it has been demonstrated that fexaramine, an agonist of FXR, contributes to alleviating insulin resistance and lipid accumulation in NAFLD mice." (PMID 40243350, 2025). "This fact may explain the downregulation of genes related to β-oxidation (CPT1A, CPT1B, and UCP3) in supplemented calves and may represent a protection mechanism against the development of diet-induced insulin resistance." (PMID 36837780, 2023). "Instead, stimulation of Cpt1a or interventions in the Acc system have had beneficial effects on insulin resistance and adiposity without apparent side effects." (PMID 23056479, 2012).
prostate carcinoma (31 papers, 2016 to 2025). A carcinoma that arises from epithelial cells of the prostate gland. "The growth of prostate cancer may be aided by a stress state caused by reactive oxygen species (ROS) that is linked to CPT1A overexpression." (PMID 37033619, 2023). "Androgens may raise the levels of CPT1A and the accumulation of reactive oxygen species, which are closely linked to prostate cancer cell proliferation and differentiation." (PMID 37033619, 2023). "It was recently demonstrated that in prostate cancer cell models, overexpression of Cpt1a is associated with a significant increase in intracellular lipase activity, a step that liberates fatty acids from triglyceride stores, which can then be used for β-oxidation." (PMID 34228639, 2021). "CPT1A is overexpressed in prostate cancer and is associated with a high tumor grade." (PMID 29907133, 2018). "In prostate cancer, CPT1A knockdown decreased FAO but increased sensitivity to etomoxir through the suppression of AKT kinase and promotion of caspase-3, thereby repressing tumor growth." (PMID 40016582, 2025). "Selective inactivation of the signal transduction adapter p62/Sqstm1 in adipocytes, secretion of osteopontin, and upregulation of CPT1A expression drive prostate cancer invasion." (PMID 41219902, 2025). "At the molecular level, succinylation of a specific protein, for example, CPT1A, causes succinylation of SP5 at K391, which activates the master signaling pathway PDPK1-AKT/mTOR and promotes proliferation and survival of prostate cancer cells." (PMID 40865948, 2025). "The present study aimed to investigate the role of CPT1A, which is a succinyltransferase in the progression of prostate cancer (PCa)." (PMID 38494680, 2024). "For the treatment of prostate cancer, miR-124 is designed to modulate the expression of carnitine palmitoyltransferase 1A (CPT1A), which impairs the ability of cancer cells to metabolize lipid substrates." (PMID 35010124, 2022). "In prostate cancer it has been shown that fatty acid oxidation plays an important role in cancer metabolism and that targeting CPT-1A with known inhibitors such as etomoxir leads to cell apoptosis and a reduction in cell proliferation." (PMID 36180554, 2022). "In the present study, we assessed the role of a mitochondrial protein carnitine palmitoyltransferase (CPT1A) in regulating prostate cancer (PCa) cell survival and proliferation under hypoxic conditions in both cell culture and animal models." (PMID 34944922, 2021). "In this study, we examined the consequences of altered expression of the mitochondrial enzyme carnitine palmitoyl transferase I (CPT1A) in prostate cancer (PCa) cell models." (PMID 33218188, 2020). "In particular, microRNA-124 (miR-124) modulates the expression of carnitine palmitoyltransferase 1A (CPT1A) at the post-transcriptional level, impairing the ability of androgen-independent prostate cancer (PC3) cells to completely metabolize lipid substrates." (PMID 32013257, 2020). "Knockdown of CPT1A leads to down-regulation of mTOR signaling and increases of apoptosis, suggesting CPT1A promotes the growth of prostate cancer cells." (PMID 29996946, 2018). "Serial sections of whole-mount prostate samples were used to identify prostate cancer by H & E staining followed by CPT1A specific staining." (PMID 28915573, 2017). "Moreover, CPT1A supports castration-resistant prostate cancer by providing acetyl groups for histone acetylation, promoting growth and anti-androgen resistance." (PMID 41219902, 2025). "Moreover, in prostate cancer, the overexpression of CPT-1A accelerates FAO and facilitates the development and proliferation of cancer cells." (PMID 39984452, 2025). "Prostate cancer cells may have less vitality after therapy with etomoxir, irreversible inhibitor of CPT1A, and etomoxir treatment in mice reduced xenograft growth for a period of 21 days." (PMID 37033619, 2023).